AKT3 (AKT serine/threonine kinase 3)
Diseases named in the same sentence as AKT3 in open-access papers (continued):
Sharing a sentence is not in itself a finding about the gene and the disease.
esophageal cancer (1 paper, 2024). A primary or metastatic malignant neoplasm involving the esophagus. "To further investigate the correlation between FTO and AKT3 in esophageal cancer tumorigenesis, we overexpressed AKT3 in KYSE150 cells and performed an additional FTO knockdown." (PMID 38491196, 2024). "We then characterized the roles of AKT3 in esophageal cancer cell functions by several in vitro experiments." (PMID 38491196, 2024). "We found that the m6A methyltransferase METTL14 is also involved in FTO-regulated m6A modification and acts in concert with FTO to regulate AKT3 methylation in the tumorigenesis and metastasis of esophageal cancer." (PMID 38491196, 2024). "Here, we showed that AKT3 is involved in the progression of esophageal cancer, which provides the basis for further targeting the AKT3 pathway for clinical treatment of esophageal cancer." (PMID 38491196, 2024). "Moreover, we found that the m6A methyltransferase METTL14 is also involved in FTO-regulated m6A modification and acts in concert with FTO to regulate AKT3 methylation in the tumorigenesis and metastasis of esophageal cancer." (PMID 38491196, 2024). "Notably, the METTL14/FTO/AKT3 signaling network might have other normal functions in addition to influencing tumorigenesis in esophageal cancer." (PMID 38491196, 2024). "To test the potential role of FTO and AKT3 in esophageal cancer biogenesis in vivo, we injected sh-FTO- or AKT3-overexpressing KYSE150 cells subcutaneously into nude mice." (PMID 38491196, 2024). "By using transcriptome-wide m6A-seq and RNA-seq assays, we revealed that AKT3 is a downstream target of FTO and acts in concert to regulate the tumorigenesis and metastasis of esophageal cancer." (PMID 38491196, 2024). "Importantly, we revealed that FTO operates through a regulatory network of m6A modifications that involves METTL14, YTHDF1 and AKT3 signaling, providing the first insight into the mechanism of FTO-mediated esophageal cancer progression." (PMID 38491196, 2024).
fallopian tube carcinoma (1 paper, 2024). A carcinoma that arises from epithelial cells of the fallopian tube. "A report at the 2016 ASCO meeting showed a cohort of 379 patients with ovarian or fallopian tube carcinoma have been evaluated for 10 genes AKT1, AKT2, AKT3, mTOR, PIK3CA, PIK3C2B, PIK3R1, PTEN, TSC1, TSC2 in the PI3K/AKT/mTOR pathway." (PMID 38167649, 2024).
ganglioglioma (1 paper, 2018). A well differentiated, slow growing neuroepithelial neoplasm composed of neoplastic, mature ganglion cells and neoplastic glial cells. "Furthermore, the PI3K/AKT3/P21 pathway, which is predicated to be targeted by miR-519d and miR-4758, was deregulated in gangliogliomas." (PMID 29963264, 2018).
germ cell tumor (1 paper, 2021). A benign or malignant, gonadal or extragonadal neoplasm that originates from germ cells. "Interestingly, AKT3 has been shown to promote germ cell tumor migration and invasion through the regulation of EMT." (PMID 34362879, 2021).
head and neck carcinoma (1 paper, 2024). A carcinoma that arises from the head and neck region. "Among the 60 DETGs, genes such as TFAP2A, CLSPN, RASEF, HIST1H3H, AKT3, and ITPR1 were associated with metastasis to secondary sites, including the lungs, and with head and neck carcinoma." (PMID 39095857, 2024).
head and neck squamous cell carcinoma (1 paper, 2021). A squamous cell carcinoma that arises from any of the following anatomic sites: lip and oral cavity, nasal cavity, paranasal sinuses, pharynx, larynx, and salivary glands. "In the present study, we sought to identify the key regulator of CAFs in head and neck squamous cell carcinoma (HNSCC) and elucidated the vital roles of AKT3, one of the AKT isoforms, in CAFs." (PMID 33799788, 2021).
hearing loss (1 paper, 2023). "Among the genes identified via FST and XP-EHH analyses, four are actually associated with hearing loss: CADM1, ESRRB, AKT3, and ATP2B2." (PMID 37570247, 2023).
liver tumor (1 paper, 2015). "The expression levels of Akt3 and E2F3 in those liver tumor tissues with miR-424 overexpressed were down-regulated compared with control group." (PMID 26315541, 2015).
malaria (1 paper, 2021). Malaria is a serious and sometimes fatal disease caused by a parasite that commonly infects a certain type of mosquito which feeds on humans. "Genomic scans suggest that immunity genes such as AKT3 and IL13 (possibly involved in simian immunodeficiency virus defense), and G6PD, a gene involved in malaria resistance, are under positive natural selection." (PMID 32986826, 2021).
medulloblastoma (1 paper, 2022). A malignant, invasive embryonal neoplasm arising from the cerebellum. "Of note, from these 122 and 13 de-regulated mRNAs and circular RNAs only 33 and 1, respectively, were present within the de-regulated mRNAs and circular RNAs in the SHH medulloblastoma subtype compared to cerebellum, with some, e.g., circular RNA AKT3, being de-regulated in the opposite direction." (PMID 35804907, 2022).
meningitis (1 paper, 2016). A disorder characterized by acute inflammation of the meninges of the brain and/or spinal cord. "In line, a plausible mechanism in which AKT3 is involved in meningitis is by influencing the inflammatory response through influencing apoptosis of inflammatory cells." (PMID 27193124, 2016). "The identified downregulation and increased mortality during experimental meningitis confirmed a role of Akt3 during pneumococcal meningitis, although the exact mechanism remains unclear." (PMID 27193124, 2016).
mesothelioma (1 paper, 2020). A usually malignant and aggressive neoplasm of the mesothelium which is often associated with exposure to asbestos. "Both PI3K genes, PIK3CA and PIK3CD, all 3 AKT genes, AKT1, AKT2 and AKT3, as well as BCL2 gene were detected in mesothelium and mesothelioma samples." (PMID 32664372, 2020).
monocytic leukemia (1 paper, 2024). "In AML, AKT3 expression varies widely among patient samples and is counterintuitively high in mature/monocytic leukemia." (PMID 38528080, 2024). "Thus, AKT3 expression in AML samples is apparently following a counterintuitive pattern with the M4/M5 myelomonocytic/monocytic leukemia samples exhibiting the highest levels of AKT3 expression, as opposed to what happens in normal differentiation." (PMID 38528080, 2024).
multiple sclerosis (1 paper, 2021). A progressive autoimmune disorder affecting the central nervous system resulting in demyelination. "Akt3-null mice have 25% smaller brain size, and increased susceptibility to demyelination in experimental autoimmune encephalitis (EAE), a widely used model for multiple sclerosis." (PMID 34440346, 2021).
multiple system atrophy (1 paper, 2022). Multiple system atrophy (MSA) is a neurodegenerative disorder characterized by autonomic failure (cardiovascular and/or urinary), parkinsonism, cerebellar impairment and corticospinal signs with a median survival of 6-9 years. "In addition, miR-520f is also significantly upregulated in multiple system atrophy, and its expression is negatively correlated with the target gene AKT3." (PMID 35528544, 2022).
muscle atrophy (1 paper, 2023). The loss of muscle tissue due to inactivity or disease. "Our molecular docking results showed that Aloin A had good binding interactions with HSP90AA1, AKT1, CTNNB1, BCL2L1, RELA, TNF, AKT3, the ranging from −7.9 to −8.9 kcal/mol, suggesting that Aloin A stably combined with these proteins for attenuating cancer related muscle atrophy." (PMID 38180061, 2023).
Neonatal sepsis (1 paper, 2025). Systemic inflammatory response to infection in newborn babies. "Based on this, future studies can develop small molecule inhibitors or RNA interference technology specifically targeting EMX2OS/miR-654-3p/AKT3 axis, which may provide a new treatment strategy for improving the prognosis of neonatal sepsis." (PMID 40994527, 2025).
overgrowth syndrome (1 paper, 2019). A group of syndromes caused by genetic birth defects that may lead to the development of malignancies. "AKT3 is one of the genes in which this type of mutations was found in patients with severe overgrowth syndromes." (PMID 30853971, 2019).
pancreatitis (1 paper, 2024). Inflammation of the pancreas. "Among them, three genes (HMGB2, LDHA and AKT3) were reported to be closely related to pancreatitis, and no gene was reported to be associated with EBV infection." (PMID 39546499, 2024).
pneumococcal meningitis (1 paper, 2019). An acute purulent infection of the meninges and subarachnoid space caused by Streptococcus pneumoniae, most prevalent in children and adults over the age of 60. "The study on outcome included 472 culture proven pneumococcal meningitis patients and their strongest association was in AKT3, rs10157763 (OR 1·88; 95% CI 1·4–2·6; p = 9·9 × 10− 5) but this was not significant after correction for multiple testing." (PMID 31519222, 2019).
Primary microcephaly (1 paper, 2020). Head circumference below 2 standard deviations below the mean for age and gender at birth. "Three common mutations of IGF-1R and deletion of the chromosome region containing AKT3 have been identified in patients with primary microcephaly, suggesting that IGF-1R mutations and AKT3 deletion may contribute to this neurodevelopmental disorder." (PMID 32324743, 2020).
prostate adenocarcinoma (1 paper, 2019). "Exome sequencing by the Broad/Cornell group on the human prostate adenocarcinoma showed only 15% of the patients with genetic alterations in the PI3K/Akt pathway, out of which 7% alterations were in PTEN and a single case of missense mutations was observed in Akt1 and Akt3 isoforms." (PMID 31360736, 2019).
reovirus infection (1 paper, 2021). "Knockdown of AKT3, but not AKT1 or AKT2, substantially reduced the enhanced expression of IFN-β at mRNA level in BMDC infected by VSV or reovirus, suggesting that AKT3 is the possible downstream target of PI3K activation after VSV or reovirus infection." (PMID 33976210, 2021). "However, expression of AKT3 was markedly induced in BMDC upon VSV or reovirus infection, indicating AKT3 maybe the downstream target of PI3K p85 activation." (PMID 33976210, 2021). "We next knocked down AKT1, AKT2, and AKT3 and examined the expression of IFN-β in BMDC followed by VSV or reovirus infection." (PMID 33976210, 2021).
salivary gland tumor (1 paper, 2018). "Hence, these results did not only validate the transgenic mouse model used in this study, but also confirmed an oncogenic role for high Akt3 expression as driver for salivary gland tumor progression." (PMID 29282901, 2018). "Hence, we treated salivary gland tumor‐harboring mice with doxycycline (Dox), thereby abrogating transgenic Akt3 overexpression." (PMID 29282901, 2018).
sarcoidosis (1 paper, 2012). Sarcoidosis is a multisystemic disorder of unknown cause characterized by the formation of immune granulomas in involved organs. "Of the 31 TCR/JS/CCR-gene signature genes, 8/31 genes were cited in the sarcoidosis literature with CD28, IFNG, IL7R, AKT3, IL2RA, IL2RB, and STAT4 demonstrating a robust relationship with these terms." (PMID 22984568, 2012).
Sepsis (1 paper, 2023). Sepsis is defined as life-threatening organ dysfunction caused by a dysregulated host response to infection. "MiR-15b-5p notably supports or opposes endothelial migration and proliferation, in both physiological conditions and altered environments as sepsis, by targeting the protein kinase B3 (AKT3) and ICAM1/ focal adhesion kinase (FAK) pathways, respectively." (PMID 37587410, 2023).
silicosis (1 paper, 2023). Silicosis is a respiratory disease caused by breathing in (inhaling) silica dust. "Studies have shown that silencing Akt3 can partially reverse LPS-induced acute lung injury; however, few roles of Akt3 have been reported in silicosis." (PMID 37511199, 2023). "IHC and Western blot results showed that Akt3 levels were evidently elevated in the lung tissues of mice with silicosis compared to those in the control group mice, and phospho-mTOR protein levels were also increased." (PMID 37511199, 2023). "Our findings showed that miR-29a-3p promotes autophagy via the Akt3-mediated mTOR signaling pathway to suppress PF, revealing a possible therapeutic target for the treatment of silicosis." (PMID 37511199, 2023). "In this study, Akt3 was significantly upregulated in lung tissues of silicosis mice and TGF-β1-treated TC-1 cells, indicating that it might be important for the development of PF." (PMID 37511199, 2023). "In this research, we investigated the mechanism of Akt3-mediated signaling pathways in silicosis." (PMID 37511199, 2023). "We first examined the expression of Akt3 and phospho-mTOR in a mouse model of silicosis." (PMID 37511199, 2023). "Furthermore, Akt3 expression was significantly elevated in the silicosis mouse model and TGF-β1-treated TC-1 cells." (PMID 37511199, 2023). "Consistent with the results of the silicosis mouse model, in TC-1 cells treated with TGF-β1, we discovered that the mRNA expression of Akt3 increased in a dose-dependent manner, with the highest expression at 10 ng/mL TGF-β1." (PMID 37511199, 2023).
small cell lung carcinoma (1 paper, 2019). Small cell lung cancer (SCLC) is a highly aggressive malignant neoplasm, accounting for 10-15% of lung cancer cases, characterized byrapid growth, and early metastasis. "For example, in small cell lung cancer, exon 1 or 2 of PVT1 fuses to exon 2 of AKT3 (1q44) to form a chimeric transcript PVT1-AKT3." (PMID 31309249, 2019).
soft tissue tumours (1 paper, 2017). "Although Akt1 overexpression was prominent in soft tissue tumours, it was still lower than that of Akt2 or Akt3." (PMID 28209968, 2017).
tauopathy (1 paper, 2023). Neurodegenerative disorders involving deposition of abnormal tau protein isoforms (tau proteins) in neurons and glial cells in the brain. "In contrast, MG2 and MG4, disease-associated cells induced by tauopathy, exhibit higher levels of proinflammatory genes like Apoe, Spp1, Nfkb1, and Akt3, as well as STAT3, IL-8, NF-kB, and JAK/STAT signaling." (PMID 37961627, 2023).
thrombosis (1 paper, 2024). "Our findings are similar to those of other studies, in which AKT3 promoted the formation of arterial thrombosis in vivo by inactivating glycogen synthase-3 induced by thrombin." (PMID 38267920, 2024).
thyroid (1 paper, 2012). "Regarding the selected genes in other CNA/UPD areas, the AKT3/PIK3CA pathway, the KRAS/RAP1B/RAP1GAP/BRAF pathway, and the VEGFC pathway have been known to participate in thyroid carcinogenesis/cancer progression." (PMID 22558328, 2012).
tongue cancer (1 paper, 2021). A malignant neoplasm affecting the tongue. "Two independent shRNAs against AKT3 (shAKT3#4 and shAKT#5) were transfected into CAFs isolated from a surgical tongue cancer specimen." (PMID 33799788, 2021).
tuberculosis disease (1 paper, 2023). "In addition, phagosome processes and tuberculosis disease were also significantly enriched, and AKT3, CD14, FCGR3A, and CORO1A were significantly up-regulated in the MAB group." (PMID 37764178, 2023). "Interestingly, phagosome processes and tuberculosis disease were also significantly enriched, with AKT3, CD14, FCGR3A, and CORO1A being significantly up-regulated in MAB-infected patients." (PMID 37764178, 2023).
Wilms tumor (1 paper, 2023). An embryonal neoplasm characterized by the presence of epithelial, mesenchymal, and blastema components. "MiR-22-3p regulates the proliferation and invasion of Wilms’ tumor cells through the inhibition of AKT3." (PMID 37998329, 2023). "AKT3 is upregulated in Wilms’ tumors, whereas miR-22-3p is downregulated." (PMID 37998329, 2023).
ZIKV infection (1 paper, 2021). "Overexpression of the constitutively active form of Akt3 (myr-HA-Akt3 E17K) in fNSCs was shown to down-regulate autophagy induced by ZIKV infection or NS4A-NS4B co-expression." (PMID 34696510, 2021).
tumor (214 papers, 2008 to 2025). "To further substantiate the synergy between circHIPK3/miR-124/AKT3 in ESCC, we examined the association between circHIPK3/miR-124/AKT3 expression in ESCC tumor tissues." (PMID 35443871, 2022). "In this study AKT3 was notably implicated in determining the tumor phenotype and aggressiveness, although it was the prevalent isoform in a small subset of patients (3%)." (PMID 35053468, 2022). "The immunohistochemistry of 72 HNSCC patients showed that AKT3 expression in CAFs positively correlated with tumor infiltration by CAFs, tumor-associated macrophages, dendritic cells, and T cells." (PMID 33799788, 2021). "In GBM, circ-AKT3 is reported to encode AKT3-174aa, a novel tumor suppressor protein, and enhance radiation sensitivity cells by negatively regulating the PI3K/Akt pathway." (PMID 32122355, 2020). "To elucidate the detailed mechanism underlying circ-AKT3 function as a tumor suppressor in ccRCC, we first performed Western blotting assay to screen some metastasis related genes involved in the pathway of circ-AKT3-dependent inhibition of metastasis." (PMID 31672157, 2019). "AKT is postulated to contribute to gastric carcinogenesis and to influence prognosis, and our bioinformatic analysis of the TCGA dataset showed that there was significant upregulation of AKT3 RNA in CDH1-deficient tumours, but variable AKT1 expression." (PMID 31540244, 2019). "We demonstrate by in silico analysis that Akt1 is the dominant isoform harbouring gain-of-function mutations, particularly the PH domain mutation E17K, in tumour samples, whereas Akt2 and Akt3 undergo copy number variations with higher frequency." (PMID 28209968, 2017). "Based on the dysregulation patterns and functional associations, our results indicate that AKT3 is a potential central marker of tumor presence and malignancy." (PMID 29321820, 2017). "AKT has a central role in regulating apoptosis and over-expression (via amplification or mutation) of the isoform AKT3 correlates with tumour progression." (PMID 21139585, 2011). "Of note, in both of the tumour samples from this patient the observed prevalence of the AKT3 E17K mutation was ∼30%, meaning that ∼60% of the analysed cells harbour the mutation if it is heterozygous." (PMID 18813315, 2008). "AKT3-174aa, encoded by circAKT3, can act as a tumor suppressor." (PMID 40034125, 2025). "Moreover, the AKT3 isoform was evidently upregulated in OS tissues and positively associated with tumor size." (PMID 36839989, 2023). "CNA-containing genes included oncogenes showing copy number gain such as Yap1, Braf, Foxo1, and Akt3 and tumor suppressors with copy number loss such as Rb1, which may favor tumor growth." (PMID 36376321, 2022). "Mutations in AKT3 have been associated with tumor development and migration." (PMID 35443871, 2022). "Interestingly, knockdown of AKT3 resulted in a diminished increase in tumor-osteolysis associated CTGF expression after TGFβ-stimulation." (PMID 33670586, 2021). "Also, it was reported that AKT3, despite its regulatory role in proliferation and apoptosis, was associated with the infiltration of various immune cells in tumor tissues, including T cells and macrophages." (PMID 34882061, 2021). "AKT3 is an oncogene associated with the regulation and metastasis of tumor cell survival." (PMID 32913235, 2020). "One hypothesis is that gain of AKT3 expression is associated with worsening tumor biology and phenotypic de-differentiation." (PMID 27611696, 2016). "However, the downregulation of the AKT3 gene in READ tumor indicated that the molecular mechanism underlying PHLPP2-associated READ progression might not be as simple as they appear, and should be examined carefully." (PMID 37737218, 2023).